BRAF (B-Raf proto-oncogene, serine/threonine kinase)
Diseases named in the same sentence as BRAF in open-access papers (continued):
Sharing a sentence is not in itself a finding about the gene and the disease.
colorectal cancer (continued). "This pilot study involving 12 patients exploring intra-tumour heterogeneity of colorectal cancer has demonstrated relative homogeneity of genetic factors (BRAF and KRAS mutations), as well as epigenetic homogeneity (in terms of DNA methylation)." (PMID 28097409, 2017). "The BRAF mutation-like subtype of colorectal cancer, including both BRAF mutated tumors and BRAF wild-type tumors with a similar gene expression pattern, can be characterized by a 58-gene signature." (PMID 29479053, 2017). "Colorectal cancer patients with the BRAF(p.V600E) mutation have poor prognosis in metastatic setting." (PMID 29479053, 2017). "Few studies have investigated the relationship between BRAF mutations and altered miRNA expression in colorectal cancer." (PMID 29115941, 2017). "The level of mutated cfDNA is prognostic in other cancer types as well, with higher levels of mutated KRAS and BRAF DNA found in colorectal cancer patients with lower survival." (PMID 29137355, 2017). "In the discovery phase, we benefited from the highest quality data and identified that RANBP2 knockdown can kill the BRAF-mutation-like subtype of colorectal cancer cells." (PMID 29479053, 2017). "In colorectal cancer, mutations of BRAF predominantly occur in codon 600, particularly leading to p.V600E mutation." (PMID 29115941, 2017). "In this study the applicability of ezrin protein expression together with MSI status and BRAF mutation status were tested in predicting disease outcome in stage II colorectal cancer." (PMID 28953975, 2017). "In summary, promising outcomes of vitamin C described in the management of KRAS and BRAF mutated colorectal cancer cells opened a new insight into treating aDTC." (PMID 28791253, 2017). "The cytotoxic effects of the copper thiosemicarbazone VLX60 differ from those of VLX50 and shows interesting features as a potential antitumor drug, notably against BRAF mutated colorectal cancer." (PMID 28415818, 2017). "We first analyzed the mutational status of KRAS and BRAF in colorectal cancers from our cohort of patients." (PMID 29115941, 2017). "Approximately 5–10% of patients with colorectal cancer harbor BRAF mutations, which has been associated with poor clinical outcomes." (PMID 28173629, 2017). "Currently, the BEACON phase III clinical trial (NCT02928224) is also evaluating the role of binimetinib in combination with a BRAF and EGFR inhibitor in BRAF mutated colorectal cancer patients." (PMID 29108355, 2017). "BRAF oncogenic mutations are observed in 10% to 20% of colorectal cancer patients and are associated with MSI-high and CIMP-high phenotypes." (PMID 28623901, 2017). "Some studies have evaluated the association between molecularly distinct colorectal cancer subtypes defined by microsatellite instability, CpG island methylator phenotype and/or BRAF mutation status and alcohol consumption." (PMID 28973012, 2017). "Patients with colorectal cancer containing a BRAF mutation or those with CIMP-positive tend to be older, smokers, women, right-sided, and have a higher-grade histology." (PMID 29115941, 2017). "The BRAF mutation is found in approximately 10% of colorectal cancer patients, as the consequence, the sample size of BRAF wild-type tumors is often sufficient, while the sample size of BRAF mutated tumors is often much smaller." (PMID 29479053, 2017). "The precise mechanism underlying this miRNA down-regulation, particularly in BRAF-mutated colorectal cancer, should be further elucidated in future studies." (PMID 29115941, 2017). "A similar tendency has been observed in studies of metastatic or recurrent colorectal cancer, where BRAF mutations are associated with worse overall survival (OS)." (PMID 29115941, 2017). "On the other hands, both mutations in KRAS and BRAF have been clearly demonstrated to predict resistance to EGFR-directed therapy in colorectal cancer." (PMID 29312543, 2017).
colorectal cancer (continued). "The combined EGFR and BRAF inhibition decreases cell proliferation and triggers apoptosis of BRAF-mutated colorectal cancer cell lines and xenografts." (PMID 29312543, 2017). "MicroRNA-31 (miR-31) plays an oncogenic role and is associated with BRAF mutation and poor prognosis in colorectal cancer." (PMID 26871294, 2016). "Mechanisms or reasons for exclusive hot spot mutations were similar to KRAS/BRAF exclusive mutations in colorectal cancer." (PMID 26848617, 2016). "Using microRNA array analysis, we recently identified that miR-31 expression was significantly upregulated in BRAF-mutated colorectal cancer compared with wild-type colorectal cancer." (PMID 26871294, 2016). "Since the CpG island methylator phenotype (CIMP) was associated with MSI and BRAF mutations in colorectal cancer, MSI has played an important role in colorectal cancer studies." (PMID 26964035, 2016). "A total of 77 colorectal cancer precursor lesions were identified with BRAF V600E mutations, 45 from male subjects, and 32 from female subjects." (PMID 26910894, 2016). "Currently, BRAF mutations are found in 35–45% of colorectal cancers and they are considered to be a prognostic biomarker for poor prognosis in patients receiving first-line colon cancer therapies." (PMID 27927793, 2016). "Serrated pathway colorectal cancers (CRCs) are characterised by a BRAF mutation and half display microsatellite instability (MSI)." (PMID 27661107, 2016). "As breast cancers and colorectal cancers have similar BRAF and KRAS mutation spectra, it is logical that both cancers have a similar response to both cetuximab and panitumumab." (PMID 27655662, 2016). "In this study, we investigated several aspects of the molecular epidemiology of KRAS and BRAF mutations in sporadic colorectal cancer precursor lesions." (PMID 26910894, 2016). "This study provides a comprehensive analysis of RNF43 and ZNRF3 in cohorts of colorectal cancers stratified by BRAF mutation and MSI status." (PMID 27661107, 2016). "The overall BRAF mutation rate in colorectal cancer precursor lesions in this studied population was 12.1% by standardized rate, similar to previous studies." (PMID 26910894, 2016). "In our data, BRAF mutations were detected in 50.0% of serrated adenomas, 36.9% of hyperplastic polyps and 7.1% of other types of colorectal cancer precursor lesions." (PMID 26910894, 2016). "We characterized our primary tumors for BRAF mutation; the frequencies we obtained were in agreement with published reports on the occurrence of BRAF V600E mutation in sporadic and Lynch associated colorectal cancers." (PMID 27047543, 2016). "MiR-31-5p was one the most up-regulated miRNA in colorectal cancers with BRAF p.V600E oncogenic mutation, compared with wild-type BRAF and play a role in cell invasion and proliferation in this tumor type." (PMID 26646588, 2016). "Considering that a mutation of another oncogene BRAF plays a role in tumor aggressiveness of retractable colorectal cancer in down stream pathway of KRAS, a role of BRAF was studied." (PMID 27924922, 2016). "Since RKO was the among the only in vitro colorectal cancer model holding BRAF mutation; we also extended the BRAF mutation analysis to the primary tumors." (PMID 27047543, 2016). "3-BrPA at 110 μM was shown to suppress the growth of colorectal carcinoma cells with KRAS or BRAF mutations surviving glucose starvation." (PMID 27863474, 2016). "3-BrPA preferentially suppressed the growth of some colorectal carcinoma cells with KRAS or BRAF mutations which survived glucose starvation." (PMID 27863474, 2016). "BRAF-mutated colorectal cancers have an unfavourable prognosis, and, thus, these patients are less likely to experience liver-limited disease and the option of surgical treatment of their metastases." (PMID 25318602, 2015).
colorectal cancer (continued). "In this study, our primary aim was to assess the changes in the DNA methylation profile and also to examine KRAS and BRAF mutations in the progression of normal epithelium to colorectal cancer." (PMID 26291085, 2015). "Mutations in KRAS and BRAF genes seem to occur in a mutually exclusive manner, and both are suggested as integral components for an effective molecular classification of colorectal cancer." (PMID 25929517, 2015). "BRAF mutations have also been identified as having a detrimental effect on prognosis in microsatellite stable (MSS) or MSI-H colorectal cancer cohorts, but results are conflicting." (PMID 26496026, 2015). "In an era of personalized medicine for BRAF mutation in metastatic melanomas, a targeted therapy has been investigated in advanced colorectal cancer harboring a mutation of BRAF." (PMID 25983749, 2015). "Somatic mutations in KRAS, NRAS, and BRAF genes are related to resistance to anti-EGFR antibodies in colorectal cancer." (PMID 25954997, 2015). "We have established a NGS mutation assay for the detection of KRAS, NRAS, and BRAF mutations in clinical FFPE samples of colorectal cancer and have demonstrated a high preclinical and clinical performance." (PMID 25954997, 2015). "The BRAF proto-oncogene is a serine-threonine kinase that is mutated in approximately 10% of colorectal cancers." (PMID 26496026, 2015). "Most frequent activating mutations of BRAF found in colorectal cancer almost invariably result in valine substituting glutamate at residue 600 (BRAF V600E) and occur at a frequency of 10–15%." (PMID 25983749, 2015). "The RALA pathway is robustly active in colorectal cancer cell lines harboring KRAS or BRAF driver mutations." (PMID 26033452, 2015). "Recently, Prahallad and coworkers demonstrated that in colorectal cancer this resistance is caused by the ability of BRAF V600E to induce an inhibitory feedback circuit towards the EGFR." (PMID 26065894, 2015). "By targeting MCL-1 via mTOR inhibition, colorectal cancers with Kras or BRAF mutations are sensitized to BCL-2/BCL-XL inhibition." (PMID 26134786, 2015). "The additional mutations in minor KRAS, NRAS, and BRAF were detected in 20% of the colorectal cancer patients in the PEAK study." (PMID 25954997, 2015). "For example, the discovery that effective treatment of BRAF-mutated colorectal cancers requires inhibition of both BRAF and EGFR has resulted in several combination trials." (PMID 25422355, 2015). "Using miRNA array analysis, we recently discovered that microRNA-31 (miR-31) expression is significantly up-regulated in BRAF-mutated colorectal cancers compared with that in wild-type colorectal cancers." (PMID 26090613, 2015). "Collectively there are 296 colorectal cancers with somatic mutation data that show an 8.1% BRAF V600E mutation rate." (PMID 25613750, 2015). "Regarding BRAF gene, a recent study suggests that BRAF mutations occur in 10–20% of sporadic colorectal cancer and are closely associated with the MLH1 methylation." (PMID 26557847, 2015). "In colorectal cancer, BRAF mutations are tightly correlated with two molecular features: CpG island methylator phenotype (CIMP) and microsatellite instability (MSI)." (PMID 25983749, 2015). "BRAF mutation is a common genetic alteration in human epithelial cells including lung and colorectal carcinomas, with frequencies of up to 20%, whereas sarcomas rarely possess the mutation." (PMID 29061943, 2015). "From a clinical perspective, BRAF-mutated colorectal carcinomas (CRCs) are frequently addicted to this mitochondrial survival pathway, resistant to apoptosis and poorly responsive to standard chemotherapeutics and EGFR monoclonals." (PMID 26084290, 2015). "Recently, MMR status, KRAS and BRAF mutation status have attracted remarkable attention due to their potential prognostic and predictive role in colorectal carcinomas." (PMID 25929517, 2015).
colorectal cancer (continued). "BRAF V600E mutation is often present in colorectal carcinoma with CpG island methylator phenotype and microsatellite instability." (PMID 25983749, 2015). "Frequent overlap of BRAF P-loop mutations with KRAS mutations has been previously reported in colorectal carcinomas." (PMID 26506417, 2015). "Colorectal cancers arising via the serrated pathway are often associated with BRAF V600E mutation, CpG island methylator phenotype (CIMP), and microsatellite instability." (PMID 24812557, 2014). "Recent studies emphasize the role of BRAF as a genetic marker for prediction, prognosis and risk stratification in colorectal cancer." (PMID 25005754, 2014). "Mutation profiles were 100% concordant for KRAS, NRAS, and BRAF, and were highly concordant for recurrent alterations in colorectal cancer." (PMID 25164765, 2014). "An association between BRAF mutations and female has been reported in patients with colorectal cancer." (PMID 24979348, 2014). "Our current data suggest that KRAS mutations, irrespective of mutated codon, are inversely associated with MSI-high and BRAF mutations in colorectal cancer." (PMID 24885062, 2014). "Mutations in the KRAS and BRAF genes are frequently found to be mutually exclusive in colorectal cancer." (PMID 25267307, 2014). "KRAS codon 12 and 13 mutations have been inversely associated with BRAF mutation in colorectal cancer." (PMID 24885062, 2014). "The coexistence of PI3K and KRAS mutations and the mutual exclusion of KRAS and BRAF mutations had been previously reported in a subset of patients with colorectal cancer." (PMID 25313136, 2014). "There is also a significant association between CIMP-H, MSI, and BRAF mutations in colorectal cancers." (PMID 24812557, 2014). "It has been reported that aberrant activation of ERK has been linked to BRAF mutations in various cancers including colorectal cancers." (PMID 25514788, 2014). "Oncogenic activation of signaling pathways downstream of the EGFR, as induced by mutated KRAS or BRAF, is important for the progression of colorectal cancer." (PMID 25267307, 2014). "CIN has not been extensively studied on a genome-wide basis in relation to BRAF mutational status in colorectal cancer." (PMID 24651849, 2014). "Several studies have now identified that MAPK pathway reactivation constitutes a mechanism of therapy resistance in BRAF V600E mutated colorectal carcinomas that are treated with Vemurafenib." (PMID 25409462, 2014). "In the present study, we examined the associations of specific KRAS and BRAF mutations with clinicopathological and tumour biological characteristics, and survival, in 525 incident cases of colorectal cancer from a prospective population-based cohort study." (PMID 24020794, 2013). "Both MEK/ERK and GSK3 signaling pathways are thought to be affected in early stages of colorectal cancer formation due to frequent mutations in KRAS/BRAF and APC genes respectively." (PMID 23919615, 2013). "A non-significant trend for better survival with fluorouracil/leucovorin + irinotecan (vs. fluorouracil/leucovorin alone) was detected in colorectal cancer stage III patients with BRAF V600E mutation." (PMID 24298448, 2013). "Since the discovery of BRAF mutations in colorectal cancer, a vast body of literature has been published on the association of BRAF mutations with other genetic and epigenetic events in CRC." (PMID 23845441, 2013). "The most common activating BRAF mutation in colorectal cancer is the V600E mutation, which is present in 5–15% of all tumors, and up to 80% of tumors with high microsatellite instability (MSI) harbor this mutation." (PMID 24298448, 2013).
colorectal cancer (continued). "In colorectal cancers from White patients, we identified significantly more mutations in BRAF (17%) than in either the Asian (4%, P = 0.004) or Black (7%, P = 0.014) cohorts." (PMID 24066160, 2013). "Activating KRAS and BRAF mutations predict unresponsiveness to EGFR-targeting therapies in colorectal cancer (CRC), but their prognostic value needs further validation." (PMID 24020794, 2013). "In conclusion, the results from this large prospective cohort study provide further support to the accumulating evidence of BRAF-mutated microsatellite stable colorectal cancer having a particularly impaired prognosis." (PMID 24020794, 2013). "The BRAF mutation represents an additional risk factor only in some subpopulations of colorectal cancers, in others having limited prognostic value." (PMID 24073892, 2013). "Recently, BRAF mutation testing has been introduced as a marker in differentiating sporadic colorectal cancers from Lynch syndrome." (PMID 24759670, 2013). "Results from this cohort study demonstrate sex-related differences in the prognostic value of BRAF mutations in colorectal cancer, being particularly evident in men." (PMID 24020794, 2013). "In this study, we extended the number of screened CpG loci compared with previous studies performed in context of BRAF mutations to identify new BRAF mutation-specific methylation changes in colorectal cancer." (PMID 23324568, 2013). "In our consecutive colorectal cancer material BRAF V600E mutation was found in 78% of MSI-H and 8% of MSS tumors (p < 0.0001)." (PMID 24298448, 2013). "In this study, we have investigated the prognostic significance of KRAS codons 12 and 13, and BRAF mutations in incident colorectal cancer from a large prospective cohort study, with particular reference to sex-related differences." (PMID 24020794, 2013). "BRAF V600 selective inhibitors have been approved for the treatment of V600 mutation positive metastatic melanoma, but the response rates in colorectal cancer are poor." (PMID 24298448, 2013). "For positive BRAF mutation, the colorectal cancers were located in the sigmoid colon (1 patient) and the rectum (2 patients)." (PMID 24759670, 2013). "Colorectal cancer has been analyzed with the BRAF V600E mutation specific antibody and most studies find high sensitivities and specificities (98.8–100%) in comparison with PCR-based methods or sequencing." (PMID 24298448, 2013). "In stage II-III colorectal cancer, BRAF mutation was confirmed a marker of poor survival only in subpopulations involving microsatellite stable and left-sided tumors, with higher effects than in the whole population." (PMID 24073892, 2013). "In conclusion, BRAF mutation rate was low in multiple primary cancer with colorectal cancer and stomach cancer in a Korean population." (PMID 24759670, 2013). "The purpose of this study is to identify mutation in the BRAF gene in multiple primary cancers with colorectal cancer and stomach cancer." (PMID 24759670, 2013). "For KRAS analysis, this was concordant across all technologies, however the BRAF mutation at codon 600 was called in 1/3 colorectal carcinoma samples though at a low coverage equal to 4.38% and only by 1/4 analysis (IonTorrent)." (PMID 23922754, 2013). "Activating oncogenic mutations of BRAF have been described in many malignancies, including cutaneous melanoma (67%), colorectal carcinoma (12%), non-small cell lung carcinoma (NSCLC; 3%), and KIT wild-type GIST (13%)." (PMID 23470635, 2013). "The pooled log HR of BRAF mutation effect on patient survival in colorectal cancer for cohort and RCT studies were 0.88 (0.60–1.16) and 0.61 (0.28–0.94), respectively." (PMID 23056577, 2012). "Colorectal cancers arising via the serrated neoplastic pathway are characterised by a high frequency of BRAF mutation, MSI and CIMP." (PMID 23110075, 2012). "We found that BRAF mutation increases the risk of mortality in colorectal cancer patients for more than two times; HR = 2.25 (95% CI, 1.82–2.83)." (PMID 23056577, 2012).